RNU6-363P (RNA, U6 small nuclear 363, pseudogene)
Gene: Small nuclear RNA gene on chromosome 5 (31,595,565 to 31,595,669, reverse strand). Ensembl gene ENSG00000199765.
Homologues: Orthologues: chimpanzee U6 (97% identical), macaque U6 (94% identical), dog U6 (86% identical), rabbit U6 (77% identical). Paralogues in human: RNU6-664P (89% identical), RNU6-338P (88% identical), RNU6-356P (88% identical), RNU6-698P (87% identical), RNU6-38P (86% identical), RNU6-641P (86% identical), RNU6-1158P (85% identical), RNU6-116P (85% identical), RNU6-1316P (85% identical), RNU6-140P (85% identical), RNU6-949P (85% identical), RNU6-1124P (84% identical), and 1284 more.